IL6 (interleukin 6)
Diseases named in the same sentence as IL6 in open-access papers (continued):
Sharing a sentence is not in itself a finding about the gene and the disease.
cardiovascular disease (continued). "IL-6 has been identified as a marker for metabolic disorders and cardiovascular disease, although its exact in vivo pathophysiological significance remains unknown." (PMID 32708379, 2020). "Thus, in obese subjects, there is a risen expression of proinflammatory cytokines, comprising TNFa, IL6, IL8, and MCP1 and the associated cardiovascular disease." (PMID 32373073, 2020). "For this reason, IL-6 is considered a pleiotropic cytokine involved in normal function of the immune system, hematopoiesis, metabolism, and the pathogeneses of metabolic disorders and cardiovascular diseases." (PMID 31073335, 2019). "IL-6 plays a critical part in cardiovascular disease, which could activate ECs and modulate the extracellular lipids." (PMID 31237148, 2019). "Boosting the level of IL-6, induce the inflammatory reaction and expand the cardiovascular disease." (PMID 31780924, 2019). "The level of IL-6 is relevant to the incidence and prognosis of cardiovascular disease, which supports the hypothesis of inflammation." (PMID 32802107, 2019). "Concordantly, studies have shown the association of inflammatory markers especially CRP which is among the GPS score variables, interleukin-6 (IL-6), tumor necrosis factor alpha, pentraxin 3 and neutrophil-to-lymphocyte ratio with poor prognosis in cardiovascular diseases." (PMID 31096693, 2019). "Since oxidative stress is a hallmark of inflammation, which represents an important pathomechanism for the development and progression of cardiovascular disease, we also measured the inflammation marker IL-6 that was increased, at least by trend, in all of the used disease animal models." (PMID 31661873, 2019). "Fourth, IL-6 inhibition may be effective for the prevention of cardiovascular disease, since IL-6 elevates platelet count, fibrinogen concentration and activity of coagulation." (PMID 30423923, 2018). "Thus, there is substantial data implicating IL-6 in the initiation as well as progression and maintenance of cardiovascular disease through reductions in NO, increases in vascular superoxide, and alterations in vascular function." (PMID 29186034, 2017). "Our findings show that the sleep disturbance-associated inflammatory factor IP10 as well as IL6 and hs-CRP may indicate an underlying inflammatory state, which has been shown to be associated with increased risk for cardiovascular disease in menopausal women." (PMID 28060925, 2017). "IL-6 could be considered as a major regulator of cardiovascular disease initiation and progression through circulating levels alternation." (PMID 27648032, 2016). "IL-6 might play a key role in the development of cardiovascular disease through metabolic, endothelial, and coagulant." (PMID 26849353, 2016). "Chronically elevated TNF-α and IL-6 levels are markers of systematic inflammation linked to negative health outcomes such cardiovascular disease (CVD) and insulin resistance." (PMID 26378783, 2015). "There is strong evidence that IL-6 serum concentration increases with age and it is associated with an increased risk of cardiovascular disease (CVD) mortality, independent of CRP level." (PMID 26366318, 2015). "Interleukin- 6 (IL-6) is inflammatory markers that the main its effects is the induction of hepatic CRP production which to be an independent, major risk factor for cardiovascular disease." (PMID 26153197, 2015). "High levels of IL-6 predicted incident cardiovascular disease and death." (PMID 25722960, 2015). "High levels of IL-6 predicted death among those with cardiovascular disease." (PMID 25722960, 2015). "Moreover, IL-6 is an important contributor to the development of cardiovascular disease (CVD) in RA patients." (PMID 25860297, 2015). "Positive affects may reduce stress-induced elevations of inflammatory and coagulation factors, such as fibrinogen and interleukin-6, which are crucial in cardiovascular diseases, and reduce vulnerability to infectious illness." (PMID 25432074, 2014).
cardiovascular disease (continued). "Prior studies also found that IL-6, TNF-α, and CRP are associated with cardiovascular diseases." (PMID 27429271, 2014). "Cytokines, TNF α, IL-6, JAK1 and STAT3 as markers of inflammation response may play a major role in the risk for cardiovascular disease, which is also recognized as essential mediator of pathological aging." (PMID 25524239, 2014). "The mechanism by which OSAS is associated with cardiovascular disease is not fully understood, but activation of the inflammatory cascade, potentially involving TNF-α, IL-6, or C-reactive protein (CRP), may be an underlying cause of these disease states." (PMID 24895539, 2014). "Both fibrinogen and IL-6 are biomarkers of inflammation related with cardiovascular diseases." (PMID 25100442, 2014). "IL-6 is a biomarker of inflammation in cardiovascular diseases and stimulates maturation of iDCs." (PMID 24932497, 2014). "Elevated CRP and IL-6 has been shown to predict development of cardiovascular disease." (PMID 23410093, 2013). "Hyper-inflammatory IL-1β enriched monocytes may be a major source of IL-6 production and systemic inflammation in HIV-infected adults, and may contribute to the risk for all-cause mortality and cardiovascular disease in treated HIV infection." (PMID 24086545, 2013). "IL6, IL8 and MCP-1 are inflammatory cytokines associated with cardiovascular disease." (PMID 22883023, 2012). "Perivascular adipose tissue increasingly is recognized as an important source of adipokines and proinflammatory cytokines, including IL-6, but its role in cardiovascular disease remains unclear." (PMID 19936194, 2008). "In addition, it is well appreciated that IL-6 induces hepatic CRP production, which is an independent risk marker of cardiovascular disease." (PMID 19936194, 2008). "Besides, in elderly IL-6 plasma levels act as a marker of subclinical cardiovascular diseases, depending also on visceral fat amount (Franceschi, personal communication) and on strong genetic control." (PMID 16571118, 2006). "Notably, studies have shown that IL-6 is an independent predictor of cardiovascular disease in PLWH, regardless of traditional atherosclerotic risk factors." (PMID 40718411, 2025). "Among them, interleukin 6 (IL-6), tumor necrosis factor-α (TNF-α), and fibroblast growth factor 23 (FGF-23) are robust independent predictors of all-cause mortality in stage 5 CKD patients, with IL-6 also serving as a reliable classifier of clinically overt cardiovascular disease." (PMID 41295836, 2025). "Although cardiovascular disorders are often associated with elevated cytokines and chemokines, correction for cardiovascular comorbidity in our analysis did not alter the results for any markers except IL-6." (PMID 39922907, 2025). "Despite the reduced number of participants in the cardiovascular disease group (only 4 participants), all those inflammatory cytokines were detected in this disease group, with statistically significant levels (compared to control group) being observed mainly for IL-1β and IL-6." (PMID 39328992, 2024). "The outcome measurements were cardiometabolic indices and risk factors for metabolic and cardiovascular diseases, including anthropometric index (body weight, BMI, WC), BP, lipid profile (TG, TC, HDL, LDL), glycemic markers (FBG, Hb1AC, Insulin), and inflammatory markers (CRP, IL-6, TNF-α)." (PMID 39285289, 2024). "These genetic analyses serve as examples for how MR may inform all stages of drug development, including anticipation of results from ongoing clinical trials investigating inhibition of IL-6 signaling for the prevention of cardiovascular disease and preservation of kidney function." (PMID 38550933, 2023). "A recent study suggested that CHIP carriers with genetic deficiency of IL-6 signaling (by carrying IL6R p.Asp358Ala versus wild-type) had a greater reduction in cardiovascular disease risk when compared to non-CHIP carriers with genetic IL-6 signaling deficiency." (PMID 38104193, 2023).
cardiovascular disease (continued). "Therefore, we believe that in patients with SLE, IL-6 may retain the deleterious role in cardiovascular disease that has been shown in the general population." (PMID 37762312, 2023). "Considering the increases of the cardiovascular risk markers IL-6, SAA, and CRP after controlled exposure to zinc and/or copper-containing welding fumes, our finding of elevated levels of CDR1as adds another potential risk marker for cardiovascular diseases after exposure to Zn/Cu metal particles." (PMID 35915466, 2022). "It is also possible that IL-6 may be a marker of cardiovascular disease rather than a risk factor per se." (PMID 36028849, 2022). "For inflammatory and hemostatic biomarkers, genetic studies suggest that IL-6 (a pro-inflammatory cytokine) and several coagulation factors are causal for cardiovascular disease, but such studies do not support a causal role for C-reactive protein and fibrinogen." (PMID 28477314, 2017). "Finally, we evaluated whether low-dose acetylsalicylic acid, which is frequently prescribed to seniors for the prevention of cardiovascular disease, affects IL-6 and CRP concentrations." (PMID 27274758, 2016). "However, the relative risk associated with high IL-6 was not significant among those without cardiovascular disease—healthy older women." (PMID 26549941, 2015). "Thus, the downregulation of TNF-α and IL-6 is necessary in the treatment of cardiovascular disease." (PMID 25371725, 2014). "This study further suggests that an absent interleukin-6 release by inflamed RA joints into the circulation may account for this unaltered cardiovascular disease risk." (PMID 23968456, 2013). "This response is characterized by increased production of proinflammatory and proatherogenic cytokines, such as interleukin-6 (IL-6) and tumor necrosis factor (TNF), both involved in the pathogenesis of cardiovascular diseases." (PMID 40001466, 2025). "Similar to other infections (e.g. HIV, sepsis, pneumonia), TB-induced cardiovascular disease likely stems from proinflammatory cytokines (e.g. TNF, IL-6, Il1β) that impair endothelial function, resulting in plaque rupture, and vascular occlusion." (PMID 40475250, 2025). "Multiple studies have shown that in SARS-CoV-2 patients with cardiovascular disease, elevated markers of thrombo-inflammatory activation like CRP, IL-6, and troponins are predictors of mortality." (PMID 40951379, 2025). "Previous 2x2 factorial MR studies have identified combination therapies primarily within cardiovascular disease between PCSK9 and CETP inhibition, NPC1L1 and HMGCR inhibition, and IL-6 and PCSK9/CETP/NPC1L1 inhibition." (PMID 38962682, 2024). "CRP is an acute inflammatory protein and is mainly synthesized by interleukin-6 (IL-6)-dependent hepatic biosynthesis, and elevated CRP levels in the serum are an independent predictor of cardiovascular disease." (PMID 38233747, 2024). "Induction of both interleukin 6 (IL6) and transglutaminase 2 (TG2) expression participates in human and experimental cardiovascular diseases." (PMID 38650935, 2024). "For patients with cardiovascular disease, CRP levels positively correlated with AST (r = 0.44, p = 0.006), ALT (r = 0.334, p = 0.043), LDH (r = 0.428; p = 0.011), IL6 (r = 0.704, p = 0.003) and fibrinogen (r = 0.602, p < 0.0001)." (PMID 38474287, 2024). "The highest IL-6 levels were recorded in patients with DM, HTN, and cardiovascular disease (119.3 pg/mL), consistent with existing research indicating that comorbidities exacerbate inflammation in RA patients." (PMID 39469275, 2024). "Aspirin reduces the expression of several inflammatory markers in cardiovascular disease (CVD), such as hs-CRP, IL-6, MCP-1, M-CSF, and TNF-α." (PMID 38836066, 2024). "In our study, for patients with cardiovascular disease, CRP levels positively correlated with AST, ALT, LDH, IL6 and fibrinogen." (PMID 38474287, 2024).
cardiovascular disease (continued). "Previous 2×2 factorial MR studies have identified combination therapies primarily within cardiovascular disease for PCSK9 and CETP inhibition, NPC1L1 and HMGCR inhibition, and IL-6 and PCSK9/CETP/NPC1L1 inhibition." (PMID 37398493, 2023). "Inflammaging, characterized by increased expression of pro-inflammatory cytokines, IL-1, IL-6, and TNF-α, was demonstrated in elderly people with cardiovascular diseases." (PMID 37676301, 2023). "We demonstrated that the non-traditional cardiovascular risk factors, the TG/HDL ratio, IL-2, IL-6, IL-17A, and INF-γ, were significantly increased in children with MetS than those without MetS, and may therefore be used as biomarkers to predict future cardiovascular disease." (PMID 37892418, 2023). "We first assessed CAEC pro-inflammatory cytokine production for IL-6, TNF-α, IL-18 and IL-1β, which are four important players for the development of cardiovascular diseases together with the anti-inflammatory cytokine IL-10." (PMID 36992409, 2023). "Neutralization of IL-6 and CCL5 has been suggested to be beneficial in cardiovascular disease, including atherosclerosis." (PMID 37476204, 2023). "A rise in inflammatory markers, such as interleukin 6 (IL-6) and C-reactive protein (CRP), are potent predictors of impaired kidney function and the development of cardiovascular disease in CKD patients." (PMID 36359271, 2022). "Intake of virgin olive oil, rich in HT, was shown to be more effective than refined olive oil in reducing levels of interleukin-6 (IL-6) and C-reactive protein (CRP), recognized inflammatory markers in cardiovascular disease." (PMID 35408740, 2022). "The increased plasma ACE level may result in an increase in the expression levels of interleukin-6 (IL-6) and kallikrein (KLK1), which subsequently increases coronary plaque vulnerability, ulceration, and thrombosis, leading to an increased risk and mortality of cardiovascular diseases." (PMID 35885904, 2022). "Given the imbalance in research studies between interleukin-6 and the other members of the IL-6 cytokine family, it is time to reconsider the involvement of the OSMR/gp130 as well as the LIFR/gp130 complexes in human cardiovascular diseases." (PMID 35163735, 2022). "For instance, a link between cardiovascular diseases and SARS-CoV-2 infection is represented by high IL-6 levels in patients with severe disease progression." (PMID 35967380, 2022). "Given the disproportionate burden of cardiovascular disease in patients with CKD and the inflammatory nature of both these conditions, there is growing interest in repurposing IL‐6 inhibitors to treat CVD in CKD." (PMID 33393675, 2021). "Studies show that IL-6 is a biomarker with better sensitivity and characteristics than CRP for the diagnosis of cardiovascular disease." (PMID 33436103, 2021). "Circulating levels of the cardiovascular disease biomarkers: ADMA, hs-CRP (high-sensitivity C-reactive protein), and IL-6 were significantly increased in the circulatory system of HIV patients." (PMID 34640478, 2021). "Among the cardiovascular disease patients, the level of CRP and IL-6 was generally decreased after 12 weeks of the n-3 supplement." (PMID 34822400, 2021). "IL-6 and TNF-α are fundamentally acknowledged as inflammatory indicators in rats suffering from cardiovascular disorders." (PMID 34526481, 2021). "In particular, a chronic increase of plasma levels of pro-inflammatory cytokines such as interleukins IL-6, IL-1β, IL-17, and TNF-α is known to characterize cardiovascular diseases including IHD." (PMID 34112104, 2021). "Studies have shown that main neuroactive cytokines involved in hypothalamic inflammatory mechanisms related to cardiovascular diseases are TNF-α, IL-6, IL1-α/IL-1β, and IL-10." (PMID 33967677, 2021). "Upregulation of major cardiovascular disease related proinflammatory cytokines, TNF-α, IL-1β and IL-6, were inhibited with anti-LOX-1 receptor antibody treatment." (PMID 32182251, 2020).
cardiovascular disease (continued). "IL-1β, TNF-α, and IL-6 stimulated the liver to produce high-sensitivity CRP (hs-CRP), which had a strong relationship with the recurrent events of cardiovascular diseases as shown in several randomized clinical trials." (PMID 29403392, 2018). "In patients with T2DM and established cardiovascular disease, canakinumab reduced markers of inflammation (hs-CRP and IL-6) compared with placebo." (PMID 27737744, 2016). "The intake of virgin olive oil, rich in polyphenols, was shown to be more effective than refined olive oil in producing a decrease in interleukin-6 (IL-6) and C-reactive protein (CRP) levels, recognized inflammatory markers in cardiovascular disease." (PMID 25988120, 2014). "In addition to modifying IL-1α, IL-1β, IL-6, TNF-α, and IL-17A levels, five nights of sleep restriction are accompanied by increased heart rate; both proinflammatory cytokines and hypertension are important risk factors for development of cardiovascular disease." (PMID 24367384, 2013). "In cardiovascular disease, elevated CRP and interleukin (IL)-6 levels correlate with adverse events." (PMID 23657512, 2013). "In the last years, different markers of inflammation (such as CRP, IL-6, and TNF-alpha, among others) have been studied in prediction of coronary events; on this regard, CRP is the most important marker for cardiovascular disease." (PMID 23690772, 2013). "Recent studies are now demonstrating that IL-6 and TNF-alpha are stronger predictors of cardiovascular disease than C-reactive protein." (PMID 17374166, 2007). "In a subgroup of patients without diagnosed cardiovascular disease, preoperative cardiac biomarker concentrations were higher in patients with high preoperative IL-6 concentrations." (PMID 40491666, 2025). "Clinical evidence demonstrates that patients with advanced periodontitis exhibit higher circulating IL-6 and CRP levels correlated with reduced flow-mediated dilation, confirming the inflammatory–vascular link between periodontal infection and cardiovascular disease." (PMID 41294894, 2025). "Inflammation driven by proinflammatory polarized macrophages can promote cardiovascular disease via excessive activation of the NF-κB and NLRP3 inflammasome pathways, triggering the release of proinflammatory cytokines (IL-1β, IL-6, IL-18) and the generation of oxidative stress molecules." (PMID 40940785, 2025). "suPAR, IL‐6, and especially their combination independently predicts all‐cause mortality and MACE in T1D without known cardiovascular disease." (PMID 40619914, 2025). "We aimed to investigate the prognostic value of suPAR and IL‐6 in a cohort of individuals with T1D without known cardiovascular disease." (PMID 40619914, 2025). "In the subsequent multivariable analysis, we confirmed the absence of cardiovascular disease, low levels of IL-6 and PCT, and TLR4 rs4986790 AG/GG genotypes as independent predictors of potential hospitalization and reduction of severe or fatal disease course." (PMID 38433829, 2024). "The other parameters (pre-existing lung and cardiovascular diseases, older age, IL-6 mRNA, and IFN-ɣ mRNA) did not remain significant in the logistic regression model." (PMID 39339947, 2024). "As IL-6 and TNF-α play a role in cardiovascular disease pathogenesis, they might be useful as therapeutic targets." (PMID 37887854, 2023). "Extensive literature supports the proatherogenic role for IL-6 in cardiovascular disease, and IL-6 inhibition has consequently been proposed as a novel method for vascular protection." (PMID 36903354, 2023). "Although IL-6 plays a central role in the inflammatory response, there has been a relative lack of evidence linking IL-6 and cardiovascular disease." (PMID 36119741, 2022). "These suggested that the effects of IL6 on cardiovascular diseases are independent of the effects of CRP." (PMID 34168680, 2021).